LRP2 (LDL receptor related protein 2)
Diseases named in the same sentence as LRP2 in open-access papers (continued):
Sharing a sentence is not in itself a finding about the gene and the disease.
gout (11 papers, 2013 to 2022). A condition characterized by painful swelling of the joints, which is caused by deposition of urate crystals. "We confirmed that rs2544390, an SNP of LRP2, has an association with gout in the Japanese population." (PMID 31975031, 2020). "The clarification of the association between LRP2 and gout progression will lead to a better understanding of the molecular pathogenesis of gout and to novel therapeutic strategies against gout, using LRP2 as a molecular target." (PMID 31975031, 2020). "LRP2 is thought to have a possible association with urate regulation and gout susceptibility by playing an important role in urate mobilization via endocytosis." (PMID 31975031, 2020). "In conclusion, the association between a mutation of LRP2 and gout is confirmed in addition to association with SUA." (PMID 31975031, 2020). "The LRP2 rs2544390 was examined for association with gout in Japanese male, Chinese, New Zealander and European cohorts." (PMID 30123371, 2018). "Examples include evidence for a non-additive interaction of sugar-sweetened drinks consumption with a urate-associated variant of SLC2A9 in determining the risk of gout, and alcohol intake with LRP2 in determining the risk of hyperuricaemia and gout." (PMID 28566086, 2017). "A prominent serum urate- and gout-associated locus in Oceanic populations is LRP2 (encoding low-density lipoprotein receptor-related protein 2)." (PMID 28679452, 2017). "In our study, the SNP rs2544390 in LRP2 was found to be associated with the development of gout in the Chinese population, a result that was further confirmed in Asians by a meta-analysis from three studies in Chinese and Japanese populations." (PMID 26147675, 2015). "With regard to gout, the population-specific effects at LRP2 have been proven, i.e., rs2544390 polymorphism is associated with a risk for gout in a combined Māori and Pacific Island cohort." (PMID 26147675, 2015). "In the present study, we investigated the association between gout and these variants of LRP2 with 741 clinically diagnosed male gout patients and 1,302 controls." (PMID 24366390, 2014). "This study aimed to test for an association of LRP2 rs2544390 with gout and serum urate in European Caucasian and Eastern and Western Polynesian ancestral groups of New Zealand." (PMID 24286387, 2013). "In Japanese the T allele of single nucleotide polymorphism (SNP) rs2544390 in the LRP2 gene has been associated with elevated serum urate by genome-wide scanning and is associated with gout in Japanese, conferring a moderate risk of odds ratio (OR) = 1.32." (PMID 24286387, 2013). "The T allele of a single nucleotide polymorphism (SNP: rs2544390) in lipoprotein receptor-related protein 2 (LRP2) is associated with higher serum urate and risk of gout in Japanese individuals." (PMID 24286387, 2013). "LRP2 SNPs (rs2390793, rs2544390, and rs16856823) are associated with blood uric acid and increased gout susceptibility in Japanese and Chinese populations." (PMID 35813212, 2022). "Similarly, evidence has been demonstrated for interaction of sugar-sweetened beverage consumption with a urate-associated variant of SLC2A9 and alcohol intake with LRP2 in determining the risk of gout and the risk of HU and gout, respectively." (PMID 28679452, 2017). "The population-specific effects of LRP2 in gout have been proven; for instance, the T allele of rs2544390 was found to be associated with increased risk of gout in a combined Māori and Pacific Island cohort, whereas a protective effect was found in European subjects." (PMID 26147675, 2015). "Furthermore, we first identified the association between LRP2 and gout in a Chinese population and confirm the association in Asians." (PMID 26147675, 2015). "In addition, we are the first to identify the association between LRP2 and gout in a Chinese population and to confirm this association in Asians." (PMID 26147675, 2015).
gout (continued). "Additional experiments are needed to clarify the potential biological mechanisms and links between LRP2 and hyperuricemia and gout." (PMID 35813212, 2022). "Since the association between LRP2 and SUA was reported, several association studies for the Japanese population have been conducted, because gout is a consequence of hyperuricemia." (PMID 31975031, 2020). "Our study provides clues to a better understanding of the pathogenesis of gout and has the potential to lead to novel therapeutic strategies against gout using LRP2 as a molecular target." (PMID 31975031, 2020). "Our study aims to test variants in two genes abundantly expressed in the kidney, LRP2 and COMT, for their association with uric acid and gout." (PMID 26147675, 2015). "In the present study, we aimed to test variants in the LRP2 and COMT genes, both of which are abundantly expressed in the kidney, for associations with uric acid and gout in a Chinese population." (PMID 26147675, 2015). "Although further studies of LRP2 are necessary to reveal the relationship between LRP2 variants and gout, our study at least revealed that LRP2 is not a strong genetic risk for gout." (PMID 24366390, 2014). "Our study is the first to reveal that an SUA-related gene LRP2 is not involved in gout susceptibility." (PMID 24366390, 2014). "Although we found no studies reporting that LRP2 transports urate, LRP2 variants could have an association with gout risks because gout is a consequence of hyperuricemia." (PMID 24366390, 2014). "Therefore, further studies of LRP2 and COMT genes in larger samples will be performed to confirm the relationship between these loci and gout together with gene-environment interactions." (PMID 26147675, 2015). "Although no studies report that LRP2 transports urate, LRP2 is a multi-ligand receptor and expresses in many tissues including kidney, suggesting a direct and/or indirect relationship with gout." (PMID 24366390, 2014).
melanoma (10 papers, 2017 to 2025). A malignant, usually aggressive tumor composed of atypical, neoplastic melanocytes. "LRP2 (rs2302694) mutations were detected in a range of cancers, with melanoma (28.18%), uterine sarcoma (17.99%), and lung squamous cell carcinoma (16.32%) with the highest mutation rates." (PMID 38455474, 2024). "A total of 221 melanoma patients with LRP2 mutations were used to evaluate the effect of immunotherapy." (PMID 35834061, 2022). "There were significant differences in mutation frequencies among different tumor types, with the highest mutation rates of LRP2 in melanoma (28.18%), uterine carcinosarcoma (17.99%) and lung squamous cell carcinoma (16.32%)." (PMID 35834061, 2022). "In cancer, LRP2 exhibits context dependence: melanomas acquire LRP2, and its knockdown curtails proliferation, whereas several epithelial cancers epigenetically silence it, linking low expression to dedifferentiation and poor survival." (PMID 41374987, 2025). "We have previously demonstrated that LRP2 gene and protein expression is acquired in a subset of melanoma tumors." (PMID 36980716, 2023). "Continuous expression of LRP2 in melanoma is critical for cell maintenance, and low expression of this gene significantly reduces melanoma cell proliferation and survival." (PMID 36851274, 2023). "LRP2 expression has been shown to be crucial for cell maintenance in malignant melanoma, and siRNA-mediated reduction of LRP2 in melanoma cells significantly decreased melanoma cell proliferation and survival rates." (PMID 32373524, 2020). "Another study indicated that LRP2 is expressed more frequently in melanoma samples compared to nevus samples, and siRNA-mediated knockdown of LRP2 significantly decreases proliferation of melanoma cells." (PMID 39346724, 2024). "Finally, it has been reported that LRP2 is expressed in a subset of melanoma cell lines and melanoma tumors, and that LRP2 in melanoma cells is involved in receptor-mediated endocytosis." (PMID 36980716, 2023). "Lack of LRP2 expression in stromal and immune cells is consistent with our previous immunohistochemical evaluation of melanoma tumors." (PMID 36980716, 2023).
Nephropathy (10 papers, 2020 to 2025). A nonspecific term referring to disease or damage of the kidneys. "Evaluating the genes associated with kidney disease in the enrichment analysis, LRP2, which was downregulated, was found to be of particular interest." (PMID 36012119, 2022). "Of note, LRP2 was later identified to be the main antigen in the tubular basement membrane immune deposits in anti-brush border antibody disease (anti-LRP2 nephropathy), which is associated with MN features." (PMID 34899763, 2021). "Together with the finding of a third case among 224 elderly patients studied, this raises the issue of the underdiagnoses of LRP2 nephropathy, on top of the potential association to B-cell malignancy." (PMID 32701075, 2020). "On the other hand, male Lrp2 KO mice fed a WD developed severe kidney damage accompanied by aberrant blood chemistry." (PMID 38984983, 2024). "Changes in LRP2 expression across various types of human nephropathy are heterogeneous, but given the conclusive role for megalin in vitamin D uptake, disease specific changes in megalin expression likely impact mineral-bone metabolism." (PMID 35098216, 2021). "Here we present a case of anti-LRP2 nephropathy in a young Chinese woman who presented with nephrotic syndrome and normal kidney function, and achieved complete remission after prednisone and CTX treatment." (PMID 32831033, 2020). "Anti-LRP2 nephropathy can also present as nephrotic syndrome in young patients and complete remission from nephrotic syndrome may be achieved after immunosuppressive therapy." (PMID 32831033, 2020). "Anti-LRP2 antibody was identified in serum, consistent with a diagnosis of anti-LRP2 nephropathy." (PMID 32831033, 2020). "As the optimal treatment for anti-LRP2 nephropathy was unknown, prednisone, cyclophosphamide (CTX) or rituximab were used." (PMID 32831033, 2020).
Alzheimer disease (9 papers, 2012 to 2022). A progressive, neurodegenerative disease characterized by loss of function and death of nerve cells in several areas of the brain leading to loss of cognitive function such as memory and language. "LRP2, whose ligand ApoE is known for the risk of Alzheimer’s disease, is expressed in brain and facilitates the clearance of the Aβ peptide, that is, the cause of Alzheimer’s disease." (PMID 24366390, 2014). "Together with the fact that urate has anti-oxidant effects, LRP2 variants carrying the risk of Alzheimer’s disease might have an association with SUA variation." (PMID 24366390, 2014). "Two other variants of LRP2, rs2229268 and rs3755166, are also found to have associations with dyslipidemia and Alzheimer’s disease, respectively, which also could have a relationship with SUA in human." (PMID 24366390, 2014). "In neurons the most important are LRP-1 and LRP-2, even it is thought that a causal factor in Alzheimer's disease (AD) is the malfunction of this process which cause impairment intracellular signaling as well as storage and/or release of nutrients and toxic compounds." (PMID 22934024, 2012). "LRP2 is also connected with diabetic nephropathy, Lowe syndrome, Dent disease, Alzheimer’s disease (AD) and gallstone disease." (PMID 30837596, 2019). "In this context, age and/or disease-related alterations in LRP1 and LRP2 levels could reduce the efflux of Aβ and concourse to the pathogenesis of Alzheimer’s disease." (PMID 36243724, 2022). "Vitamin D's active form (1,25-dihydroxyvitamin D3) maintains and stabilizes intracellular signaling pathways involved in memory and cognition by increasing VDR and LRP2 expression in the choroid plexus and helping clear neurotoxic β-amyloids involved in Alzheimer's disease (AD) pathogenesis." (PMID 32523528, 2020). "CSF samples from patients with Alzheimer’s disease demonstrated reduced LRP1 and LRP2-bound Aβ, which may contribute to the elevated brain Aβ in Alzheimer’s disease." (PMID 33066423, 2020). "Interestingly, in brain tissues from patients diagnosed with Alzheimer's disease, LRP-2 expression has been immunohistochemically detected in neurons, even being up regulated in damaged neurons." (PMID 22934024, 2012). "Instead, they have received more attention in the context of Alzheimer’s disease, in particular LRP1 and LRP2 of which Aβ, like tPA, is a ligand." (PMID 36243724, 2022). "Based on these findings, it is tempting to speculate that regulation of Lrp2 expression by nuclear PSA-lacking NCAM contributes to regulating Lrp2-mediated neural functions and Alzheimer ́s disease pathology." (PMID 29051583, 2017).
Obesity (9 papers, 2014 to 2024). Accumulation of substantial excess body fat. "Although they did not fully meet the criteria defined previously, variants rs183867145, rs147058423 and rs189273089 (found in LRP2 gene) were also considered as potential risk variants associated with obesity." (PMID 33921825, 2021). "Similar to the other genes associated with monogenic forms of obesity, LRP2 is also involved in the regulation of the leptin-melanocortin pathway." (PMID 25158045, 2014). "Furthermore, despite the fact that our results have not been replicated yet in other obese individuals, they are important to raise awareness of the LRP2 gene as a possible candidate as a novel monogenic cause of obesity." (PMID 25158045, 2014). "A comprehensive bioinformatics analysis found de novo and compound heterozygote sequence variants with a damaging effect on genes previously associated with obesity in mice (LRP2) and humans (UCP2), among other intriguing mutations affecting ciliary function (DNAAF1)." (PMID 25158045, 2014). "Therefore, LRP2 acts as a key mediator of the food intake-suppressing effects of clusterin, and its absence can cause obesity in rodents (as previously demonstrated)." (PMID 25158045, 2014). "Intriguingly, some of these variants were harboured in genes involved in the pathophysiology of obesity (such as LRP2 and UCP2), providing the foundation for future research in this field." (PMID 25158045, 2014). "A study of miRNA based modulation of obesity also reported LRP2 as a putative target of miR-130a, with roles in lipid metabolism." (PMID 24725334, 2014). "Understanding the relationship between diet and Lrp2-mediated sex-dependent protection or injury may provide novel targets for managing obesity and T2D." (PMID 38984983, 2024). "Mice with an endothelial specific knockout of LRP2 exhibited obesity when fed normal chow diet." (PMID 34066779, 2021). "In addition, we identified rare heterozygous missense variants in ADCY3 (p.G1110R), MYT1L (p.R807Q), ISL1 (p.I347F), LRP2 (p.R2479I, and p.N3315S) and a hemizygous missense variant in GRPR (p.L87M) (each in one patient), possibly contributing to the obesity phenotype in these patients." (PMID 32153512, 2020). "Nonetheless, in light of recent results using the Tie2-Cre; Lrp2flx/flx mice, our preliminary data using Slco1c1-CreERT2; Lrp2flx/flx mice indicate that LRP2 at the BBB is not specifically involved in the development of obesity." (PMID 34066779, 2021). "The current study suggests that LRP2 in the BBB is not involved in leptin transport in vitro or obesity in mice under normal chow diet feeding conditions." (PMID 34066779, 2021). "Although LRP2 has not been suspected to participate in obesity, a study with whole-exome sequencing analysis suggests that LRP2 could play a role in the development of early-onset obesity." (PMID 32332780, 2020).
prostate carcinoma (8 papers, 2013 to 2023). A carcinoma that arises from epithelial cells of the prostate gland. "Given the dependence of prostate cancer on androgens and the prior report of LRP2 polymorphisms with prostate cancer aggressiveness, we examined megalin protein and LRP2 gene expression in patients with prostate cancer." (PMID 36875158, 2023). "In one study, polymorphisms in the megalin gene LRP2 are associated with prostate cancer recurrence, prostate cancer–specific mortality, and the effectiveness of androgen deprivation therapy." (PMID 36875158, 2023). "LRP2 gene polymorphisms have also been studied in regards to prostate cancer given the influence of steroid hormone uptake by endocytic receptors in prostate epithelial cells." (PMID 32373524, 2020). "Germ-line polymorphisms in the LRP2 gene may be associated with an increased risk for recurrence in prostate cancer." (PMID 36727052, 2022). "LRP2 variants have previously been associated with prostate cancer and pancreatic cancer risk." (PMID 31164161, 2019). "Germ-line polymorphisms in the LRP2 gene may be associated with increased risk for recurrence in prostate cancer and somatic mutations in LRP2 have been identified in gastric cancer." (PMID 29088295, 2017). "For example, as a receptor, LRP2 plays an important role in the physiological and nervous systems of several organs, including the kidney, lungs, and intestines, and has been implicated in the development of fibrosis-related diseases and breast and prostate cancers." (PMID 36851274, 2023). "Together, the prostate cancer data support that LRP2 expression is highest in normal tissues and lower in tumor areas." (PMID 36875158, 2023). "1,25D-treated LNCaP and 22Rv1 prostate cancer cells also exhibited decreased LRP2 expression, but to a lesser extent than the benign cells." (PMID 36875158, 2023). "Other genetic studies have associated a polymorphism located in the LRP2 promoter with AD risk, regardless of the ApoE genotype, as well as some LRP2 germ-line polymorphisms with increased risk of prostate cancer recurrence." (PMID 36012187, 2022).